TLR8 (toll like receptor 8)
Description:
Endosomal receptor that plays a key role in innate and adaptive immunity. Controls host immune response against pathogens through recognition of RNA degradation products specific to microorganisms that are initially processed by RNASET2. Recognizes GU-rich single-stranded RNA (GU-rich RNA) derived from SARS-CoV-2, SARS-CoV-1 and HIV-1 viruses. Upon binding to agonists, undergoes dimerization that brings TIR domains from the two molecules into direct contact, leading to the recruitment of TIR-containing downstream adapter MYD88 through homotypic interaction. In turn, the Myddosome signaling complex is formed involving IRAK4, IRAK1, TRAF6, TRAF3 leading to activation of downstream transcription factors NF-kappa-B and IRF7 to induce pro-inflammatory cytokines and interferons, respectively.
Synonyms: CD288; hTLR8; IMD98; TLR-8
Tractability: Small molecule: a drug acting on it is in phase 2 or 3 trials; a structure with a bound ligand is known; a high-quality ligand is known; it belongs to a druggable protein family. Antibody: UniProt places it where antibodies can reach, with high confidence; UniProt predicts a signal peptide or a membrane-spanning region; its Gene Ontology location is reachable by antibodies, with medium confidence. PROTAC: UniProt records ubiquitination sites on it; its protein half-life has been measured; a small molecule that binds it is known. Other modalities: a drug acting on it is in phase 2 or 3 trials.
Target class: Toll-like and Il-1 receptors; Membrane receptor
Chemical probes: ENPATORAN, selgantolimod (high quality)
Gene: Protein-coding gene on chromosome X (12,906,620 to 12,923,169, forward strand). Ensembl gene ENSG00000101916.
Subcellular location: Endosome membrane
Pathways (Reactome):
Immune System: Toll Like Receptor 7/8 (TLR7/8) Cascade; Trafficking and processing of endosomal TLR
Disease: SARS-CoV-2 activates/modulates innate and adaptive immune responses
Gene Ontology:
Molecular function: DNA binding; double-stranded RNA binding; protein binding; single-stranded RNA binding; pattern recognition receptor activity; RNA binding; signaling receptor activity
Biological process: cellular response to mechanical stimulus; defense response to virus; positive regulation of canonical NF-kappaB signal transduction; positive regulation of innate immune response; positive regulation of interferon-alpha production; positive regulation of interferon-beta production; positive regulation of interleukin-1 beta production; positive regulation of interleukin-8 production; positive regulation of type II interferon production; response to virus; toll-like receptor 8 signaling pathway; canonical NF-kappaB signal transduction; immunoglobulin mediated immune response; innate immune response; positive regulation of interleukin-6 production; toll-like receptor signaling pathway; defense response; endolysosomal toll-like receptor signaling pathway; immune response; response to other organism; signal transduction
Cellular component: endosome membrane; external side of plasma membrane; endolysosome membrane; endoplasmic reticulum membrane; Golgi membrane; plasma membrane
Homologues: Orthologues: chimpanzee TLR8 (99% identical), macaque TLR8 (97% identical), guinea pig TLR8 (75% identical), pig TLR8 (74% identical), mouse Tlr8 (71% identical), rat Tlr8 (71% identical), rabbit TLR8 (57% identical), tropical clawed frog tlr8 (50% identical). Paralogues in human: TLR7 (43% identical), TLR3 (20% identical), TLR2 (18% identical), TLR5 (18% identical), TLR10 (17% identical), LRRC32 (17% identical), TLR1 (16% identical), TLR4 (16% identical), TLR6 (16% identical), NRROS (15% identical), IGFALS (14% identical), CD180 (14% identical), and 10 more.
Diseases named in the same sentence as TLR8 in open-access papers:
TLR8 is named in the same sentence as 229 diseases in open-access papers, as found by Europe PMC text mining. Sharing a sentence is not in itself a finding about the gene and the disease. The quoted sentences say what the papers report.
viral infections (50 papers, 2009 to 2026). "TLR8 gene variants have been associated with the severity of some viral infections or, conversely, with a protective effect modulating the cytokine response (rs3764880) in HIV but with disease progression in patients with tuberculosis." (PMID 39940907, 2025). "Even though TLR8-mediated recognition has been associated with viral infections, new findings link TLR8 sensing to viable bacterial infection and unmodified RNAs, a hallmark of viable bacteria." (PMID 24967632, 2014). "Furthermore, mutations in TLR8 have also been reported to influence the severity of some viral diseases." (PMID 35215078, 2022). "Such an overexpression of TLR8 associated with higher cytokine response could be explained by the incapacity of the innate and, secondary, the adaptative immune system, to clear the viral infection, as suggested by other authors." (PMID 33917265, 2021). "TLR8 variants and their agonists have been involved in cell activation, increasing IFN-γ production in viral infections." (PMID 39940907, 2025). "TLR7 and TLR8 are endosomal sensors of single-stranded RNA that play essential roles in the defence against viral infection and in the induction of B cell systemic autoimmunity." (PMID 40336011, 2025). "Neutrophils are known to possess a repertoire of pattern recognition receptors (PRRs), including TLR8, enabling them to detect viral infections by sensing foreign ssRNA." (PMID 39811276, 2025). "Imiquimod is a ligand for Toll-like receptor (TLR) 7 and TLR8 and is used in dermatology for the treatment of several cutaneous diseases, including actinic keratosis and basal cell carcinoma, as well as viral diseases such as condyloma accuminatum." (PMID 36982669, 2023). "TLR8 expression has been documented to increase around 2 to 6 h after some viral infections such as human parechovirus 1 (HPEV-1) and influenza virus (H5N1)." (PMID 35215078, 2022). "Single nucleotide polymorphism (SNP) in TLR8 has shown to impair immune response and functional effects during HCV, which suggests that individuals with SNPs respond differently to viral infections." (PMID 35215078, 2022). "TLR8 agonists have the potential for use as immunomodulatory components in therapeutic modalities for viral infections such as chronic HBV (CHB) and HIV." (PMID 34960669, 2021). "TLR8 agonists are mainly utilized to treat viral diseases, as well as adjuvants for malignancy and vaccines for infectious disease." (PMID 34804111, 2021). "R848 (resiquimod), a small-molecule compound of imidazoquinoline, is an agonist of TLR7 and TLR8 that is currently used clinically to treat infectious viral diseases and tumours." (PMID 34340711, 2021). "These genes include TLR8, which is involved in Th1 differentiation, relevant in viral infections, or BTK (Bruton Tyrosine Kinase), involved in downstream signaling events of the B-cell receptor." (PMID 34349112, 2021). "Preclinical and clinical studies have shown that downstream inflammatory immune mediators from TLR8 signaling result in preliminary efficacy for the treatment of cancer and viral infections." (PMID 34960669, 2021). "CL075, a dual agonist for TLR-7 and TLR-8 that mimics single-stranded RNA, was selected for study given the high burden of viral infections in young children." (PMID 35185860, 2021). "TLR7 and its closely related receptor, TLR8, play an important role in the immune response to viral infection; they recognize single-stranded RNAs as natural ligand but have also been demonstrated to sense imidazoquinolines and nucleoside analogues." (PMID 33578955, 2021). "The originality of our work lies in the stimulation of TLR7 and TLR8 which reproduce in vitro a viral infection by the activation of innate immune system and produce type I IFN." (PMID 33585507, 2020).
viral infections (continued). "Exposure to ssRNA, which models viral infections and induces trophoblast pro-inflammatory responses via the activation of TLR8 and non-TLR8 signaling pathways, also decreased ABCG2 mRNA and BCRP protein expression in EVTs." (PMID 31561453, 2019). "On the other hand, the robust activation of intrahepatic cellular immunity via TLR8 needs to be tightly controlled, both during natural infection or if a TLR8 agonist is to be exploited for therapy of chronic viral infections." (PMID 24967632, 2014). "TLR7 and TLR8 are involved in the response to viral infections and recognize GU-rich short single-stranded RNA as well as small synthetic molecules such as midazoquinolines and nucleoside analogues." (PMID 23700487, 2013). "TLR3, TLR7 and TLR8 have been implicated in responses to virus infection in animal models, TLR3 through recognition of dsRNA and TLR7 and TLR8 through recognition of ssRNA and small nucleoside analogues." (PMID 23824215, 2013). "Among the TLRs recognizing bacterial patterns, TLR1, 2 and 4 were expressed strongest, whereas TLR8 as a sensor of viral infections showed highest expression of the RNA-responsive receptors." (PMID 20843333, 2010). "Opposite to our findings, acute viral infections would increase TLR8 expression via type I IFN autocrine mechanism, respectively." (PMID 20946625, 2010). "TLR7 and TLR8, located in the endosome, act as anti-viral receptors for recognizing single strand RNA (ssRNA), which is present at various phases of viral infection from viral entry to replication." (PMID 19527497, 2009). "TLR7 and TLR8 are two other TLRs that play a role in IFN production in response to viral infection." (PMID 41011507, 2025). "We then examined whether HIV is sensed by TLR7 or TLR8 in the context of viral infection using an established model of cell-to-cell transmission." (PMID 37256770, 2023). "Overall, these correlative observations in patients might suggest that some viruses have developed an evasion mechanism that impairs the innate immune response via TLR8 inhibition and highlights the importance of TLR8 in viral infections." (PMID 35215078, 2022). "However, further work is warranted to better understand the specific mechanisms that govern the expression, activation, and regulation of TLR8 by viral infections." (PMID 35215078, 2022). "However, the response against viral infection after TLR8 activation highly depends on the type of cell infected." (PMID 35215078, 2022). "In the mature brain, TLR8 might be quiescent under normal conditions, but is being activated in response to adequate stimuli, like tissue injuries or viral infection, and may induce according responses in neuronal morphology." (PMID 35507634, 2022). "Our data shows that oral administration of specific-TLR8 agonist enhanced the production of effector molecules by innate and adaptive lymphoid cells, which can possibly be explored for their direct antiviral effect during viral infections." (PMID 34960669, 2021). "Endosomal TLRs recognising RNA such as TLR8 play an important role in viral diseases." (PMID 33557133, 2021). "TLR8 has been identified as a natural receptor for single-stranded RNA and is thought to act as an effective activator of the innate immune response after viral infection." (PMID 32963529, 2020). "However in PAMs, TLR3, TLR7, and TLR8 mRNA expressions were significantly up-regulated by the viral infection." (PMID 24712747, 2014). "TLR-8 is activated in viral infections producing type I IFN." (PMID 22114589, 2011). "HERV-K elements can activate Toll-like receptor 8 (TLR8), and lead to neuronal apoptosis via TLR and selective insulin receptor modulator 1 (SIRM1) signaling, a shared apoptotic mechanism associated with environmental viral infections (e.g., herpes simplex virus, Epstein-Barr virus)." (PMID 35585302, 2022).
viral infections (continued). "TLR8 recognizes the invasion of viruses and induces the innate immune response; hence, it is often associated with BVD and type 3 parainfluenza caused by the same bovine herpesvirus type 1, resulting in infectious rhinotracheitis as well as other viral diseases." (PMID 34070451, 2021). "Members of the TLR family that have been shown to be involved in responses to viral infection, in part including that of SARS-CoV-2, are TLR1, TLR2, TLR3, TLR4, TLR6, TLR7, TLR8 and TLR9." (PMID 41011507, 2025). "After a viral infection, there is a rapid redistribution of MyD88 to the endosomal compartment, where the TIR domains of TLR8 phosphorylate MyD88." (PMID 35215078, 2022). "It is noteworthy that besides cancer indications, TLR8 agonists such as DN052 can be used for other indications including cancer vaccines and the treatment of viral infections including HBV." (PMID 35006413, 2020). "An IFN response is also observed following viral infections in several fish species, and upregulation of both TLR7 and TLR8 transcripts was detected in infected Atlantic salmon." (PMID 32641385, 2020). "Our experiments point towards a beneficial role for LILRA3 in virus infections, especially in ssRNA viruses, like HIV, that engage TLR8." (PMID 26969150, 2016). "Endosomal TLR3, TLR7, TLR8, TLR9 are specialized in the sensing of nucleic acids produced notably during viral infections." (PMID 24302927, 2013). "TLR-1, TLR-2, TLR-3, TLR-7, TLR-8, TLR-9, and TLR-10 induce type 1 IFN production during viral infections." (PMID 22114589, 2011). "The innate immunity cells also act against viral infections through TLRs including TLR3, TLR7 and TLR8." (PMID 19527497, 2009). "The significance of TLRs in viral infections is further highlighted by reports that TLR3, TLR7, and TLR8, along with cytoplasmic retinoic acid-inducible gene I (RIG-I)-like receptors, are instrumental in initiating innate immune responses against viral nucleic acids." (PMID 38732254, 2024). "Furthermore, the importance of TLRs in viral infections has been underscored by the finding that TLR3, TLR7, and TLR8, along with cytoplasmic RIG-I-like receptors, facilitate the initiation of innate immune responses by recognizing viral nucleic acids." (PMID 38732254, 2024). "In detail, TLR7 favors the production of cytokines involved in CD4+ T helper 17 (Th17) cell polarization (IL-1β, IL-6, and IL-23) after virus infection with MV and VSV, whereas TLR8 promotes the TH1-promoting cytokine response and type I IFN production after viral infection with ECMV." (PMID 36359340, 2022). "Whether the observed decreased TLR8 expression is RSV-specific, infants with other viral infections should be investigated." (PMID 20946625, 2010). "In addition, the activation of monocytes in SSc through TLR8 might be attributed to an EBV infection, thus supporting the notion that viral infection promotes autoimmunity through PRR signaling cascades, which affects the IFN innate immune responses." (PMID 36359340, 2022). "Given the potent effect of TLR8 agonists in inducing neutrophil-derived CCL23, and its negative regulation by IFNα, data also contribute to extend our knowledge on the complex role of neutrophils to both host defense and disease in response to viral infections." (PMID 28553619, 2017). "Lower TLR8 expression in monocytes during acute RSV infection might have a dampening effect on the early anti-viral cytokine production, upon RSV recognition, necessary to control viral infection and leading to severe LRT disease in infected infants." (PMID 20946625, 2010). "In addition, the red gene signature includes TLR2, TLR4, and TLR8, which are not prominent pDC receptors but may play a role in pDC activation under specific conditions, such as during viral infection or in inflamed tissues." (PMID 31552042, 2019).
COVID-19 (43 papers, 2020 to 2025). A disease caused by infection with severe acute respiratory syndrome coronavirus 2. "In our previous work, we observed increased frequencies of TLR3, TLR7, and TLR8 variants among severe and critical COVID-19 cases." (PMID 40943412, 2025). "In contrast, some other TLR8 variants are unrelated to COVID-19 severity." (PMID 39940907, 2025). "Increasing evidence showed that hyperactive neutrophils are associated with severe COVID-19; therefore, TLR8 may be a potential therapeutic target for severe COVID-19." (PMID 37904132, 2023). "Other X-chromosomal genes may also be implicated in COVID-19, specifically Toll-Like Receptor 8 (TLR8) and TLR adaptor interacting with SLC15A4 on the lysosome (TASL)." (PMID 34858409, 2021). "Genetic variants in TLRs (including TLR8) may affect COVID-19 susceptibility (Lee, Lee & Kong, 2020)." (PMID 34616619, 2021). "Also, we have shown that hydroxychloroquine is an effective TLR8 inhibitor attenuating the TLR8-induced IL-6 release, a cytokine associated with COVID-19 progression and mortality." (PMID 34456928, 2021). "Moreover, TLR7 and TLR8, which have been implicated in inflammasome signaling have been suggested to play an underlying role in COVID-19 severity." (PMID 33149733, 2020). "Severe and fatal COVID-19 is associated with a lower expression of TLR7 and TLR8 compared to that in survivors." (PMID 39062904, 2024). "TLR3 (p < 0.001), TLR7 (p < 0.001), and TLR8 (p < 0.001) expression levels were considerably greater in COVID-19 patients compared to the control group." (PMID 38868379, 2024). "We confirmed that COVID-19 patient–derived pEVs and viral spike protein-primed pEVs induced NETs formation in a TLR8-dependent manner using TLR8 knockdown cells." (PMID 37904132, 2023). "The excessive activation of toll-like receptor 8 (TLR8) in COVID-19 [vide infra] appears to play an important role in pulmonary microvascular thrombosis." (PMID 36420234, 2022). "S1 cells exhibited the highest expressions of alarmins S100A8, S100A9, S100A12 and toll-like receptors TLR4 and TLR8, all of which are involved in neutrophil activation and were the most mature neutrophils in both KD and Severe COVID-19 patients." (PMID 36159873, 2022). "There was a significant positive correlation between LDH level and mRNA expression of TLR3 (rho = 0.39, P = 0.041), TLR7 (rho = 0.41, P = 0.008), and TLR8 (rho = 0.49, P = 0.030) in the whole COVID-19 cases." (PMID 35538443, 2022). "We also analyzed the capacity of neutrophils from COVID-19 patients to produce ROS after priming with TLR8 agonist to directly address the importance of neutrophil sensing of SARS-CoV-2 RNA in the regulation of ROS production." (PMID 35637483, 2022). "Compared to the CONTROL group, increased mRNA transcription was observed for TLRs 3, 7, 9, RIGI, and NLRP3 in the entire COVID-19 group, while TLR8 was decreased." (PMID 34315957, 2021). "We propose IFN-I (and TLR7/TLR8) and PAI-1 as potential biomarkers to predict the susceptibility to severe COVID-19." (PMID 34064104, 2021). "Although these data are limited, in aggregate they suggest that the various forms of AM all share the characteristic of activating both virus-associated (TLR3, TLR7, TLR8 or TLR9) and bacteria-associated (TLR2 and TLR4) innate receptors with severe COVID-19, KD and MIS-C." (PMID 36769320, 2023). "Therefore our data arein favor of the use of TLR8 inhibitors as integrative therapy in fighting the exaggerated inflammatory response observed in severe COVID-19 patients." (PMID 36497044, 2022). "Low TLR7 and TLR8 levels in MetS and COVID-19 comorbidity may reduce myocardial capacity to generate an antiviral response and thus blunt the immune response." (PMID 34611227, 2021).